CRP (C-reactive protein)
Diseases named in the same sentence as CRP in open-access papers (continued):
Sharing a sentence is not in itself a finding about the gene and the disease.
Insulin resistance (1,576 papers, 2005 to 2026). Increased resistance towards insulin, that is, diminished effectiveness of insulin in reducing blood glucose levels. "Higher CHDI scores were also linked to about a 1% lower probability of having insulin resistance (p < 0.0001) and elevated CRP levels, a marker of systemic inflammation (p = 0.0207)." (PMID 41559012, 2026). "Elevated CRP was also strongly linked to multimorbidity (aOR for ≥3-4 vs. no conditions: 5.96, 95% CI: 3.52-10.08, P < 0.001), as well as insulin resistance, low high-density lipoprotein, high triglycerides, and multiple adiposity measures." (PMID 42224262, 2026). "Studies have suggested an association between CRP and insulin resistance, thus increasing cardiovascular risk." (PMID 39858445, 2025). "Circulating IL-6 stimulates hepatic production of C-reactive protein, a major risk marker for atherosclerosis, and has been implicated in insulin resistance through effects on adipose and hepatic metabolism." (PMID 41007333, 2025). "Elevated CRP levels are also associated with insulin resistance, type 2 diabetes, and cardiovascular disease." (PMID 39852378, 2025). "Increased concentrations of pro-inflammatory cytokines, including tumor necrosis factor-alpha (TNF-α), interleukin-6 (IL-6), and C-reactive protein (CRP), are implicated in the development of insulin resistance and the deterioration of pulmonary function." (PMID 40142617, 2025). "Studies have shown that tumor necrosis factor-alpha (TNF-α) and C-reactive protein levels at 24–28 weeks of gestation are strongly correlated with pregnancy-associated insulin resistance, making them potential inflammatory biomarkers for GDM management." (PMID 40678778, 2025). "Collectively, these studies demonstrate that hs-CRP is consistently associated with insulin resistance, atherosclerosis, and adverse cardiovascular outcomes in T2DM and related conditions." (PMID 40725102, 2025). "Firefighters with elevated CRP have chronic inflammation, which worsens insulin resistance and raises the risk of abrupt cardiac events." (PMID 40407432, 2025). "CTI is a recently introduced index designed to assess inflammation (via CRP) and insulin resistance (via TyG), both of which are risk factors for DM and osteopenia/OP, and it is a direct, rapid indicator at no additional cost beyond standard laboratory tests." (PMID 41179881, 2025). "Elevated CRP/Alb indicates chronic low-grade inflammation, combining increased hepatic CRP synthesis and decreased albumin production, both linked to insulin resistance and endothelial dysfunction." (PMID 41302334, 2025). "In patients with pneumonia, elevated C-reactive protein (CRP) have been positively associated with insulin resistance." (PMID 40260105, 2025). "There is a positive correlation between insulin resistance and inflammatory markers, such as CRP and IL-6, suggesting that prediabetes increases the risk of developing cerebrovascular events." (PMID 41296388, 2025). "Numerous studies have confirmed a significant positive correlation between CRP and insulin resistance, supporting inflammation's independent association with both ischemic stroke risk and adverse prognosis." (PMID 40474525, 2025). "CRP, a consistent top predictor across multiple conditions, is known for its role in low-grade chronic inflammation associated with insulin resistance and cardiovascular disease." (PMID 40981199, 2025). "High doses (≥700 mg/day) have been associated with reductions in C-reactive protein (CRP) levels and improvements in insulin resistance, with well-documented protective effects against oxidative stress–related diseases, including CHD." (PMID 41049373, 2025). "New data are promising regarding the utility of the C-reactive protein–triglyceride–glucose index as a novel biomarker for insulin resistance and inflammation, as well as its association with stroke risk." (PMID 40870513, 2025).
Insulin resistance (continued). "This imbalance is associated with systemic inflammation and insulin resistance, evidenced by elevated levels of C-reactive protein (CRP), interleukin-6 (IL-6), tumor necrosis factor-alpha (TNF-α), and lipopolysaccharide-binding protein (LBP)." (PMID 40308637, 2025). "Refined carbohydrates are dietary sources with a high glycaemic index, like white bread and sugar-containing snacks, which have been associated with increased insulin resistance and higher levels of inflammation markers, including C-reactive protein (CRP)." (PMID 41280310, 2025). "These ranges are clinically relevant because central obesity and insulin resistance are associated with sustained CRP elevations mediated by IL-6 and other cytokines secreted from visceral adipose tissue." (PMID 41305609, 2025). "Hs-CRP and fasting insulin were significantly associated with insulin resistance (P values > 0.05 for all)." (PMID 40641901, 2025). "This study examines the independent and combined effects of LE8, insulin resistance (IR) and C-reactive protein (CRP) on CMM risk." (PMID 40740646, 2025). "Our data indicate that the METS-IR score is strongly associated with systemic inflammation and insulin resistance, which are often reflected in CRP and ESR levels." (PMID 40218212, 2025). "The analysis also indicates that body inflammation, as indicated by CRP, causally influences insulin resistance, as indicated by HOMA-IR." (PMID 39717478, 2024). "Insulin resistance, inferred to be directly influenced by CRP, is considered a causal factor for T2D, TGL, and HDLc." (PMID 39717478, 2024). "BMI, C-reactive protein, and race were reported to mediated the association between hyperphagia or hypersomnia and insulin resistance." (PMID 38783222, 2024). "Long-term exposure to elevated levels of CRP and IL-6 is associated with type 2 diabetes, insulin resistance, and metabolic syndrome." (PMID 39683396, 2024). "Together, insulin resistance, hypertriglyceridemia, and elevated CRP levels likely contribute to an increased risk for T2DM and, more importantly, CV disease." (PMID 39121088, 2024). "There seems to be a positive association between C-reactive protein and insulin resistance, body weight, and total body fat mass." (PMID 38397957, 2024). "In epidemiological studies, high concentrations of blood CRP and leptin were associated with high insulin resistance." (PMID 39199499, 2024). "CRP concentration is a well-established insulin resistance marker associated with T2D, while elevated levels of pro-inflammatory cytokines are biomarkers of obesity." (PMID 37396849, 2023). "Although OS and inflammation are well established in postmenopausal women, there are limited studies about pro‐oxidant‐antioxidant balance (PAB), CRP levels and their association with insulin resistance in diabetic postmenopausal women." (PMID 36577716, 2023). "The authors also observed that both higher liver fat and NAFLD were most strongly associated with higher values of systolic blood pressure, insulin resistance, triglycerides and CRP." (PMID 36674606, 2023). "Cardiovascular risks were associated with abdominal obesity, waist-to-height ratio, insulin resistance, hyperglycemia, and C-reactive protein." (PMID 37763094, 2023). "Measures of inflammation (CRP), and glucose homeostasis (insulin, insulin resistance, and blood glucose) were associated with AgeAccel.Hannum, AgeAccelPheno, and AgeAccelGrim, but not with AgeAccel.Horvath." (PMID 36752898, 2023). "CRP is a biomarker of inflammation and insulin resistance and is associated with coronary artery disease and total mortality." (PMID 37686719, 2023). "As far as we know, our study is the first to report an association between increasing admission CRP levels at admission and higher insulin resistance in patients with CAP." (PMID 38202252, 2023).
Insulin resistance (continued). "Collectively, CRP shows inhibitory effects on the insulin signaling pathway, and increased CRP with age is a potential biomarker and cause of insulin resistance and NAFLD." (PMID 37893085, 2023). "BMI was positively associated with leptin, C-reactive protein and insulin resistance, and negatively associated with Free T4, progesterone and human chorionic gonadotropin." (PMID 36520252, 2023). "Hyperhomocysteinemia, insulin resistance, and increased high-sensitivity C-reactive protein (hs-CRP) are independent risk factors for the development of cardiovascular complications." (PMID 36751256, 2023). "Collectively these data powerfully indicate that CRP deficiency can improve insulin resistance and enhanced the influence of leptin on hepatic glucose kinetics and insulin signaling in PCOS rats." (PMID 37660067, 2023). "Outstandingly, increased circulating levels of inflammatory markers such as CRP and IL-6 have been linked to insulin resistance and progression to T2DM." (PMID 38004306, 2023). "CRP is linked to hepatic insulin resistance through its involvement in impairing insulin signaling in the liver." (PMID 37891561, 2023). "Secondly, we found a high prevalence of insulin resistance, and increasing CRP levels at admission were associated with higher insulin resistance." (PMID 38202252, 2023). "In this backdrop, the present study was conducted to evaluate the role of supplementation of water-soluble vitamins in the reduction of cardiovascular risk factors such as homocysteine, insulin resistance, and CRP in prehypertensive subjects." (PMID 36751256, 2023). "Elevated CRP levels are clinically linked to the development of insulin resistance, which can ultimately lead to type 2 diabetes." (PMID 37660067, 2023). "A high body mass index (BMI) has been associated with highly sensitive C-reactive protein (hs-CRP), and insulin resistance has been associated with thyroid dysfunction and is higher in patients with vitiligo and rheumatoid arthritis." (PMID 36556950, 2022). "After multivariable regression analysis, age, visceral adipose tissue and CRP remained associated with increased insulin resistance, while canagliflozin treatment and higher NO level were associated with reduced insulin resistance." (PMID 35144596, 2022). "According to this study, insulin resistance and other biomarkers, including high sensitivity C-reactive protein and uric acid, were associated with MetS severity scores." (PMID 36684931, 2022). "The present study has enabled us to validate the association between hs-CRP and adiponectin in insulin resistance." (PMID 37654824, 2022). "In the univariate regression analysis, factors associated with insulin resistance included age, BMI, waist/hip ratio, visceral adipose tissue, canagliflozin treatment, CRP and NO." (PMID 35144596, 2022). "Hyperinsulinemia and high hs-CRP levels are associated with insulin resistance and depressed cardiovascular antinomic function." (PMID 35846489, 2022). "After multivariable regression analysis, age, visceral adipose tissue, and CRP remained associated with increased insulin resistance, while canagliflozin treatment and higher serum NO level was associated with reduced insulin resistance." (PMID 35144596, 2022). "Another study noted that the risk of developing insulin resistance in schizophrenia was closely related to CRP levels." (PMID 36090349, 2022). "In the present study, when compared to the control group, women with PCOS saw significant weight loss, improvements in insulin resistance, and hs-CRP levels following a home-based exercise program." (PMID 35547420, 2022). "Specifically, increased levels of the neutrophil count, white blood cell, and C-reactive protein (CRP) were found to be positively associated with body mass index (BMI) and index of insulin resistance in obese children." (PMID 36612926, 2022).
Insulin resistance (continued). "Normal mean values of C-reactive protein and insulin resistance index (HOMA-IR) indicated a low risk for metabolic disturbances in participants of both profiles." (PMID 35646726, 2022). "These inflammatory markers, such as tumor necrosis factor alpha (TNF-a), interleukin 6 (IL-6), C-reactive protein, and leptin, influence insulin resistance and growth hormone and cause an imbalance in protein synthesis, and lead to poor physical capacity." (PMID 35875029, 2022). "Adjusting for differences in CRP with the other covariates, except BMI or waist circumference, also weakened the insulin resistance and telomere length relationship, but the association remained borderline significant." (PMID 35586815, 2022). "Randomized clinical trials have shown that SSB consumption for three weeks results in increased C-reactive protein and is associated with metabolic disorders (dyslipidemia and insulin resistance)." (PMID 33503157, 2021). "Neck circumference was positively associated with triglycerides, homeostasis model assessment of insulin resistance, C-reactive protein, and negatively associated with high-density lipoprotein cholesterol and adiponectin." (PMID 33731171, 2021). "Higher plasma CRP levels can raise blood pressure, BMI, insulin resistance, and lipids making CRP one of the common causes of cerebral ischemia." (PMID 34925466, 2021). "Increased levels of C-reactive protein (CRP) have been reported to be associated with insulin resistance, adiposity, and other features of metabolic syndrome." (PMID 34578975, 2021). "In our MVMR analysis, attenuation of insulin resistance schizophrenia associations after controlling for CRP is consistent with inflammation being associated with both exposure and outcome, albeit “negatively” with the latter." (PMID 33711016, 2021). "The serum levels of the inflammatory marker CRP are associated with all components of the MS and with insulin resistance, endothelial dysfunction, and impaired fibrinolysis." (PMID 34202304, 2021). "As a signature typical of this disease, along with hyperglycemia and insulin resistance, the T2D altered metaproteome showed a possible association between changes in the gut microbiota and low-grade inflammation (e.g., CRP synthesis)." (PMID 35010920, 2021). "Possible mechanisms underlying the attribution of SB to cancers, like increased insulin resistance and chronic inflammation marked by higher concentrations of C-reactive protein (CRP), have been proposed in recent years." (PMID 34899835, 2021). "Insulin resistance is associated with elevated levels of proinflammatory cytokines such as C-reactive protein and IL-6, which are linked to Aβ deposition in the brain." (PMID 33597002, 2021). "On the other hand, the virulent strains of H. pylori (cag + with induction of inflammatory factors 71, IL6, CRP) and chronic inflammation affect the insulin-regulating gastroduodenal hormones and ultimately predispose the person to insulin resistance." (PMID 34922625, 2021). "Third, we used MVMR to evidence that after controlling for CRP, an archetypal general inflammatory marker, the associations between inflammation-related genetic variants for insulin resistance and schizophrenia completely attenuated." (PMID 33711016, 2021). "Higher CRP levels (> 3 mg/L vs. ≤ 3 mg/L) were associated with insulin resistance (OR = 3.27; 95% CI 1.58–6.79), dyslipidemia (OR = 2.61; 95% CI 1.40–4.86) and MetS (OR = 6.52; 95% CI 2.28–17.85)." (PMID 33299020, 2020). "We also aimed to explore the non-linear association between pulmonary function and blood glucose, insulin resistance, and C-reactive protein (CRP)." (PMID 33148273, 2020). "Few studies, however, have assessed the combined association of increased hs-CRP and body mass index (BMI) on insulin resistance, particularly in Asian populations." (PMID 33116232, 2020).
Insulin resistance (continued). "Two studies showed that insulin resistance and type 2 diabetes are associated with higher levels of C-reactive protein (CRP), interleukin-6 (IL-6), and tumour necrosis factor-α (TNF- α), which are markers of subclinical systemic inflammation." (PMID 32369922, 2020). "In our study, changes in hepatic and renal Cu and Zn contents were associated with hyperinsulinemia, insulin resistance and C-reactive protein concentration." (PMID 32172503, 2020). "It was also found that “Inactive & Sedentary LS”, high BF%, insulin resistance, and ultra-sensitive C-reactive protein were associated with the concentrations of proinflammatory biomarkers of tumor necrosis factor-α, interleukin-6, and leptin." (PMID 32694929, 2020). "Our analyses also revealed that high CRP levels are associated with the risk of insulin resistance, dyslipidemia and MetS." (PMID 33299020, 2020). "Insulin resistance is associated with an increased concentration of inflammatory markers such as C-reactive protein (CRP)." (PMID 32656036, 2020). "The diabetic patients with kidney failure exhibited the highest elevation of TLRs, Th1 cytokines and CRP in association the highest record of insulin resistance." (PMID 33442388, 2020). "After a 2-y follow-up, the Mediterranean diet was associated with decreased hsCRP, IL-6, and insulin resistance in patients with metabolic syndrome; and associated with increased adiponectin and decreased CRP in T2D patients." (PMID 30927000, 2019). "Insulin resistance plays an important role on the development of MetS caused by systemic inflammation with elevated circulating levels of CRP and TNF-α17,18." (PMID 31575927, 2019). "A statistically significant inverse relationship between vitamin D levels and fasting insulin, 2 h post glucose insulin, HOMA-IR and hs CRP, supporting the close relationship with vitamin D deficiency and insulin resistance." (PMID 31176378, 2019). "Previous studies have extensively reported the association of elevated CRP levels with insulin resistance and progression of T2DM." (PMID 31485456, 2019). "Excess secretion of cortisol is associated with cardiovascular health issues including elevated BP, truncal obesity, dyslipidemia, and insulin resistance, while c-reactive protein is a risk marker for CVD due to its role in inflammation and atherosclerosis." (PMID 31181102, 2019). "Other research suggested that ANGPTL8 levels were increased in women with PCOS and were associated with insulin resistance, hs-CRP, and free testosterone in these patients." (PMID 31346314, 2019). "Oxidative stress is associated with instigating insulin resistance by up-regulating the production of pro-inflammatory cytokines, such as CRP and TNF-α, which induce damage to proteins in the insulin cascade." (PMID 30723416, 2019). "Biomarkers measuring cancer risk were measured with fasting blood draw including insulin resistance (fasting plasma insulin and glucose levels), systemic inflammation (levels of CRP), and oxidative stress measured from urine samples." (PMID 30760246, 2019). "Insulin resistance increases inflammation and is associated with an increase in C-reactive protein (CRP), IL-6, and TNFα." (PMID 31776781, 2019). "These associations appear to be only in a small proportion mediated by an effect on MetS-related traits such as insulin resistance or visceral fat, but appear to be stronger than the associations of MetS and CRP in with PWV." (PMID 29750272, 2018). "In older adults, higher levels of inflammation factors such as C-reactive protein (CRP) and insulin resistance were associated with lower SDNN and VLF." (PMID 30540860, 2018). "Chronic exposure to elevated IL-6 and CRP levels is associated with the development of insulin resistance, the metabolic syndrome, and Type 2 Diabetes." (PMID 29704817, 2018).